GAPDH (glyceraldehyde-3-phosphate dehydrogenase)
Diseases named in the same sentence as GAPDH in open-access papers (continued):
Sharing a sentence is not in itself a finding about the gene and the disease.
tumor (continued). "GUSB was the most stable RG in group I (all samples), GAPDH in group II (paired 70 T + 70 C), followed by RPL13 in groups III (35 nonmetastatic vs 35 mccRCC) and IV (matched tumor-metastasized control group of samples)." (PMID 25225161, 2014). "Since tumor RCC is characterized by dysregulation of glucose metabolism, it is a strong support for nonconstant expression of GAPDH." (PMID 25225161, 2014). "We first screened more than 100 cases of paired samples of tumor and surrounding non-tumor tissues from HCC patients using Ponceau S staining or by determining GAPDH (glyceraldehyde-3-phosphate dehydrogenase) expression levels." (PMID 25361011, 2014). "Whereas, the levels of non-phosphorylated eIF-2α and the control glyceraldehyde 3-phosphate dehydrogenase (GAPDH) are not affected in control and tumor tissues." (PMID 22429849, 2012). "Significant expression increase from normal to tumor stomach tissues (p < 0.05) were observed in HPRT1 (p = 0.011) and 18S rRNA (p = 0.021), but not in ACTB (p = 0.058), GAPDH (p = 0.918), B2M (p = 0.740), or RPL29 (p = 0.208)." (PMID 20507635, 2010). "The ANOVA analysis (p < 0.05) confirmed that there was a significant increase in both GAPDH and HPRT1 expression levels in tumor samples compared to normal tissues." (PMID 19014639, 2008). "In the plck-GAPDH mice, which demonstrated strong activation of the non-canonical NF-κB pathway, treatment with a novel small-molecule inhibitor of NIK resulted in much lower tumor development and in a higher survival rate (patent PCT/EP2017/067306)." (PMID 35625998, 2022). "GAPDH was not an appropriate reference gene in papillary thyroid cancer (PTC) tissues, as evidenced by our bioinformatics and lab-based experiments, because its expression was dependent on tumor subtypes." (PMID 35778437, 2022). "In multivariate Cox model adjusted for stage, GAPDH HR value was lower than in univariate model and not significant (HR1.20; 95%CI .89-1.63; p = 0.23) (forest plot top line), and only tumor stage I-III was significantly correlated with survival (stage I-II HR2.36 p = 0.069; I-III HR4.22 p = 0.0002)." (PMID 23988223, 2013). "We found that stem cell-like GBM tumor subpopulations possessed higher basal levels of glycolytic activity and increased expression of several glycolysis-related enzymes including, GLUT1/SLC2A1, PFKP, ALDOA, GAPDH, ENO1, PKM2, and LDH, compared to their non-stem-like counterparts." (PMID 37420311, 2023).
cancer (451 papers, 2000 to 2025). A tumor composed of atypical neoplastic, often pleomorphic cells that invade other tissues. "Beyond this, GAPDH is implicated in multiple cancer-related biological processes, having recently emerged as a primary focus in cancer research." (PMID 39596473, 2024). "Studies have shown that GAPDH is upregulated in various cancers and is associated with poor prognosis." (PMID 39199428, 2024). "For malignant cells, consistently upregulated metabolic genes were predominantly associated with cancer hallmark pathways, including glycolysis (GAPDH, GPI and LDHA), OXPHOS (COX6B1 and ATP5MC2), and nucleotide metabolism (TK1, GUK1, NME1)." (PMID 39393173, 2024). "Increased GAPDH levels, on the other hand, are seen in a range of human cancers and are often linked to shorter survival times." (PMID 35880695, 2023). "Overexpression of GAPDH in the benzene-treated group was potentially a result of enhanced glycolysis, which is also a known cancer hallmark." (PMID 38139868, 2023). "Pyruvate kinase and GAPDH are rate-limiting enzymes in glycolysis that have been implicated in the Warburg effect and cancer." (PMID 36809274, 2023). "Overexpression of GAPDH has been reported in a variety of cancers and is associated with a poor survival rate." (PMID 37311987, 2023). "GAPDH is a glycolytic enzyme for the production of ATP and its high expression in cancer cells is associated with poor prognosis." (PMID 35804814, 2022). "Some overlapped molecules, such as HSPA8 and GAPDH, were found to be regulated by acetylation and deacetylation and associated with invasiveness of cancers." (PMID 34712204, 2021). "It possesses anti-cancer activity which is associated with the inhibition of the GAPDH-mediated effect on microtubule formation." (PMID 32370188, 2020). "This study indicates a different molecular association of GAPDH and underscores the glycation events by methylglyoxal in cancer cells." (PMID 26911935, 2016). "In RINm5F cells, GAPDH is carbonylated by NO; as a result, GAPDH is translocated to the nucleus and apoptosis is induced, indicating that GAPDH carbonylation is implicated in cancer cell death." (PMID 25859407, 2015). "Downregulated expression of the β-subunit of complex V (β-F1-ATPase) in cancer is associated with a respective increase in glyceraldehyde-3-phosphate dehydrogenase activity." (PMID 25019059, 2014). "The up-regulation of GAPDH positively associated genes correlates with more severe and/or later stages of cancer." (PMID 23620736, 2013). "Several reports unravel the participation of GAPDH in pathways that are cross-linked with cancer-specific or cancer-related phenotypes." (PMID 22964488, 2012). "In other words, blockade of GAPDH would impair multiple pathways / mechanisms forcing cancer cells to become fragile, eventually causing their death." (PMID 22964488, 2012). "Let us underline the important notion that GAPDH may be a particularly poor normalizer of RT-qPCR studies on cancer metastases." (PMID 40943534, 2025). "Similarly, the pyruvate analogue 3-bromopyruvate binds to GAPDH in cancer cells, inhibiting its enzymatic function, causing ATP depletion, and leading to apoptosis." (PMID 40630197, 2025). "GAPDH participates in glycolysis, associated with the Warburg effect observed in some cancer cells." (PMID 39610929, 2024). "The prognostic risk model based on six DMGs in our study, namely FAM83A, S100A16, E2F7, ANLN, C1QTNF6 and GAPDH, suggests that they might reveal causes of the cancer development and tumorigenesis in LUAD." (PMID 38711158, 2024). "GAPDH has been widely studied and deemed the hallmark of glycolysis in cancer metabolism." (PMID 37653101, 2023). "Targeting and inhibiting GAPDH has been implicated to the cancer treatment." (PMID 36077431, 2022). "Likewise, GAPDH protein has been linked to numerous tumorigenic mechanisms and found to be up-regulated in different types of cancer." (PMID 34199287, 2021).
cancer (continued). "Augmented expression of GAPDH is linked with autophagy in cancer cells." (PMID 34692517, 2021). "In addition to its glycolytic activity, GAPDH is implicated in regulation of proliferation, autophagy, maintenance of highly tumorogenic cancer cells, development of apoptosis, and many other processes." (PMID 33365021, 2020). "Here, (i) ENO-1 on monocytes, neurons, carcinoma cells, lymphoid cells, myoblasts and pathogenic bacteria; (ii) CK8 on carcinoma cells; (iii) p11 on endothelial cells; and (iv) glyceraldehyde-3-phosphate dehydrogenase (GAPDH) on bacteria are the best characterized ones." (PMID 25407528, 2014). "In summary, “targeting early steps of glucose metabolism (e.g. GAPDH activity) will enable us to block intracellular energy production and other critical pathways linked to it (e.g. macromolecular biosynthesis), eventually causing cancer cell death”." (PMID 22964488, 2012). "The hub proteins, such as CCT4, EZR, and GAPDH, are known to be involved in critical pathways like neutrophil degranulation and sirtuin signaling, which are linked to the altered metabolic profiles and increased cancer stemness observed in neoadjuvant-treated PDAC." (PMID 40559993, 2025). "In addition, the marked increase in GAPDH expression associated with the rapid growth of cancer cells suggests that suppression of this key reaction in glycolysis could have therapeutic value as a major strategy to control breast and other human cancers." (PMID 33615312, 2020). "Multiple activities of GAPDH in a eukaryotic cell can be linked to pro-survival or pro-apoptotic functions, depending on the enzyme’s state or protein environment, and in this review, we discuss both these activities and their relation to the physiology of normal and cancer cells." (PMID 32370188, 2020). "Further analysis showed that ceramide was inhibiting nuclear localization of GAPDH and showed that a potential mechanism of ceramide-mediated shortening of telomeres in somatic cells leads to cell senescence while maintenance of telomeres is associated with immortality of cancer cells." (PMID 24367685, 2013). "Though it is not known whether GAPDH up-regulation contributes for tumorigenesis sensu stricto, adequate data unequivocally demonstrate the existence of an association between GAPDH over-expression and pro-survival mechanisms and chemoresistance in cancer cells." (PMID 22964488, 2012). "Under pulmonary pathological conditions, particularly in cancer or inflammatory diseases, GAPDH’s role extends beyond its metabolic functions." (PMID 40129771, 2025). "Inhibition of GAPDH suppresses glycolysis in cancer cells, leading to diminished ATP production and subsequent cell death." (PMID 40950984, 2025). "Given its multiple roles and physiological functions, GAPDH has been proposed as a pharmacological target in cancer, neurological diseases, and chronic parasitic infections." (PMID 41226655, 2025). "These interactions suggest potential inhibitory effects on AKT1 and GAPDH activity, which are involved in cancer cell survival and metabolic pathways, respectively." (PMID 40933552, 2025). "In data extracted from three cancer-related Gene Expression Omnibus datasets, GAPDH expression in EC was found to be highly statistically increased (p < 0.001) when compared with normal endometrium." (PMID 40943534, 2025). "The concordance of GAPDH expression in tumors with the TICs and immune checkpoints implies a certain association between GAPDH and the TME as well as cancer development." (PMID 40046063, 2025). "Consistent with earlier research, the proto-oncogene MYC was recognized as a target of GAPDH, directly influencing the growth and proliferation of cancer cells." (PMID 41175344, 2025). "One study identified DC-5163 as a novel GAPDH inhibitor that led to cell apoptosis, decreased glucose uptake, and lactic acid production of cancer cells, so it can be a promising novel anticancer therapeutic." (PMID 40076506, 2025).
cancer (continued). "Their study was highly significant and laid the foundation for future research on the relationship between oxidative stress and GAPDH after the vitamin C treatment in cancer cells." (PMID 41300532, 2025). "Our findings demonstrated the effectiveuptake, release, and biological activity of PNAs in cancer cells,notably silencing the GAPDH gene with good efficiency." (PMID 41134300, 2025). "GAPDH, traditionally known for its role in glycolysis, has been recognized as a multifunctional protein in cancer, involved in transcriptional regulation, apoptosis, and cellular redox balance." (PMID 40933552, 2025). "We therefore focused to study GAPDH in depth as any reports pointed out the significant role in cancer-related processes." (PMID 41175344, 2025). "Direct binding of GAPDH to telomeres regulated chromosome stability, facilitating cancer cell proliferation." (PMID 41175344, 2025). "It induces elevated levels of ROS within cancer cells, which in turn suppresses glycolysis by inhibiting GAPDH activity." (PMID 40950984, 2025). "Since both proteins are overexpressed and vital for cancer cell survival, the VDAC1-interacting peptide derived from GAPDH offers a promising and potentially less toxic approach for cancer therapy." (PMID 41006687, 2025). "Among thes e genes, GAPDH exhibited upregulated expression across multiple cancer types, whereas ALB was consistently downregulated." (PMID 40463370, 2025). "Glyceraldehyde-3-phosphate dehydrogenase (GAPDH), a key glycolytic enzyme, plays an essential role in energy metabolism in cancer cells." (PMID 40630951, 2025). "While these studies highlight GAPDH's pro-apoptotic role, others point to its protective function, particularly in cancer progression." (PMID 40158853, 2025). "VC is widely used as a glycolysis inhibitor targeting GAPDH to study the role of glycolysis in cancer treatment." (PMID 39150031, 2025). "Higher expression of GAPDH correlates to worse ten-year survival across all cancer types, while the opposite is the case for HAGH (GLO2) and LDHD (PANCAN dataset)." (PMID 40461450, 2025). "Recent research has shown that increased expression of GAPDH in cancer cells improves their survival under low oxygen conditions and contributes to drug resistance." (PMID 40491606, 2025). "The results showed a significant increase in RRM2 and GAPDH expression in the cancer cell lines compared to BEAS-2B (both P < 0.05)." (PMID 40341308, 2025). "The emerging roles of GAPDH in RNA binding within cancer cells underscore its critical involvement in promoting cancer cell proliferation, rendering it an attractive target for drug development." (PMID 41175344, 2025). "Some reports have demonstrated the involvement of the RNA-binding activity exerted by GAPDH in the control of mRNA stability through interaction with 3′UTRs of several mRNAs in cancer cells." (PMID 40956859, 2025). "GAPDH (glyceraldehyde-3-phosphate dehydrogenase) is a ubiquitous enzyme central to glycolysis and has garnered attention for its multifaceted role in cancer biology." (PMID 38611852, 2024). "GAPDH is not only a key enzyme in the glycolytic pathway but also plays a significant role in the development and treatment of cancer." (PMID 39199428, 2024). "The amplification of GAPDH was completed earlier than other candidate genes as revealed by CT value, indicating that the genes are down-regulated in cancer cell lines." (PMID 38977697, 2024). "Other proteins, including GAPDH (glyceraldehyde‐3‐phosphate dehydrogenase), also show significant functions in cancer biology." (PMID 39641316, 2024). "On the other hand, GAPDH helps cancer adapt to harsh environments by regulating oxidative stress responses and apoptosis, thereby facilitating cancer progression." (PMID 39199428, 2024). "The results indicated a significant positive correlation between FOXM1 and GAPDH expression in the majority of cancers." (PMID 39062464, 2024).
cancer (continued). "Based on this, targeting GAPDH to block the energy and substrate supply to cancer cells or to induce apoptosis has garnered significant attention as an anticancer strategy." (PMID 39199428, 2024). "We evaluated the correlation between FOXM1 and GAPDH across pan-cancer samples in the TCGA database using a Pearson correlation method with a coefficient threshold of 0.3 and a p-value threshold of 0.05." (PMID 39062464, 2024). "Up-regulated GAPDH is observed in multiple cancers and has been demonstrated to promote cancer cell survival, growth, and metastases." (PMID 38811918, 2024). "DC-5163 inhibits the activity of GAPDH in various cancer cell lines and exerts anti-proliferation effects on cancer cells." (PMID 38811918, 2024). "In fact, GAPDH can act as a key enzyme in cancer cells with the Warburg effect, responsible for controlling the rate of glucose processing." (PMID 38711158, 2024). "GAPDH has pleiotropic effects on cancer progression, invasiveness, and metastasis, and its levels change under specific circumstances." (PMID 38547234, 2024). "The identification of effective GAPDH inhibitors with clinical translational value is critical for developing new therapeutic methods for cancer treatment." (PMID 38811918, 2024). "We found that GAPDH, commonly used as a reference gene, is significantly upregulated in most cancers and holds significant clinical relevance." (PMID 39062464, 2024). "Essential glycolytic enzymes such as glyceraldehyde-3-phosphate dehydrogenase (GAPDH) and the cancer cell-specific pyruvate kinase isozyme M2 are inactivated by the oxidation of Cys residues." (PMID 38674143, 2024). "GAPDH is overexpressed in multiple human cancers and its expression is positively correlated with cancer progression." (PMID 37175631, 2023). "It is possible that the enhanced stability of t-GAPDS compared to GAPDH gives regenerating and cancer cells an advantage in energy production via glycolysis." (PMID 37711387, 2023). "GAPDH is an indispensable enzyme for glucose metabolism, and is markedly upregulated in glycolytic cancer cells." (PMID 37895015, 2023). "As a result, GAPDH inhibition has been identified as a promising strategy for the treatment of cancer and other conditions." (PMID 37311987, 2023). "Further analysis revealed that co-culturing with cancer cells induced a major shift in CAF metabolism with increased expression of genes involved in glycolysis (SLC2A, GAPDH, LDHA, SLC16A3, ENO2, CA12), and the Hallmark gene set glycolysis." (PMID 37261365, 2023). "We made a preliminary exploration of the mechanisms involved and found that STS protects cancer cells against the chemotherapeutic agent ETO by reducing DNA damage, which is associated with a decrease in GAPDH levels and cell cycle arrest." (PMID 36768821, 2023). "We normalised gene expression levels across different cancer types using the housekeeping gene GAPDH." (PMID 38148640, 2023). "It has been shown that GAPDH, having glycolytic and anti-apoptotic functions, promotes the proliferation and protection of cancer cells." (PMID 37175631, 2023). "The SNO of GAPDH was detected in both human cancer tissue and SW 480 cells in comparison with the list of SNO proteins listed by Kone and our MS results." (PMID 37124724, 2023). "It is well known that cancer cells tend to shift their energy production from aerobic respiration to glycolysis (the Warburg effect) and that GAPDH expression is upregulated in cancer cells, especially under physoxic conditions." (PMID 37274277, 2023). "PKM2 is, in a certain way, reminiscent of GAPDH as it is also a tetrameric enzyme involved in glycolysis, is upregulated in cancer, and has numerous effects unrelated to its metabolic role, including in transcriptional regulation." (PMID 37947604, 2023). "The expression levels of GAPDH can vary by 80-fold between paired cancer and normal tissue samples in non-small cell lung cancer." (PMID 37274277, 2023).